MIR23C (microRNA 23c)
Synonyms: hsa-mir-23c; mir-23c
Gene: MicroRNA gene on chromosome X (20,017,088 to 20,017,187, reverse strand). Ensembl gene ENSG00000264566.
Homologues: Orthologues: chimpanzee ptr-mir-23c (100% identical).